ENSG00000260272 (novel protein)
Gene: Protein-coding gene on chromosome 16 (2,496,032 to 2,520,218, forward strand). Ensembl gene ENSG00000260272.
Genetic constraint (gnomAD): Loss-of-function variants: 17 observed, 26.27 expected, observed/expected ratio (o/e) 0.65, 90% interval 0.44 to 0.97. Missense variants: 431 observed, 546.19 expected, observed/expected ratio (o/e) 0.79, 90% interval 0.73 to 0.86. Synonymous variants: 208 observed, 242.66 expected, observed/expected ratio (o/e) 0.86, 90% interval 0.76 to 0.96.